RAMP3 (receptor activity modifying protein 3)
Description:
Accessory protein that interacts with and modulates the function of G protein-coupled receptors including calcitonin gene-related peptide type 1 receptor (CALCRL), calcitonin receptor (CALCR) and G protein-coupled estrogen receptor 1 (GPER1). Required for the transport of CALCRL and GPER1 receptors to the plasma membrane. Plays a role in cardioprotection by reducing cardiac hypertrophy and perivascular fibrosis in a GPER1-dependent manner. Together with CALCRL, form a receptor complex for adrenomedullin/ADM and intermedin/ADM2. Together with CALCR, act as a receptor complex for amylin/IAPP.
Tractability: Small molecule: a structure with a bound ligand is known; a high-quality ligand is known. Antibody: UniProt places it where antibodies can reach, with high confidence; its Gene Ontology location is reachable by antibodies, with high confidence; UniProt predicts a signal peptide or a membrane-spanning region; the Human Protein Atlas places it where antibodies can reach.
Gene: Protein-coding gene on chromosome 7 (45,157,648 to 45,188,665, forward strand). Ensembl gene ENSG00000122679.
Subcellular location: Cell membrane; Membrane
Subcellular location (Human Protein Atlas): Plasma membrane
Pathways (Reactome):
Signal Transduction: Calcitonin-like ligand receptors; G alpha (s) signalling events
Gene Ontology:
Molecular function: adrenomedullin receptor activity; amylin receptor activity; coreceptor activity; protein binding; signaling receptor regulator activity; amyloid-beta binding
Biological process: adenylate cyclase-activating G protein-coupled receptor signaling pathway; adrenomedullin receptor signaling pathway; amylin receptor 3 signaling pathway; amylin receptor signaling pathway; calcium ion transport; positive regulation of calcium-mediated signaling; positive regulation of cAMP/PKA signal transduction; positive regulation of ERK1 and ERK2 cascade; positive regulation of gene expression; positive regulation of phosphatidylinositol 3-kinase/protein kinase B signal transduction; positive regulation of protein localization to plasma membrane; positive regulation of receptor recycling; protein localization to plasma membrane; protein transport; receptor internalization; response to amyloid-beta; cellular response to estradiol stimulus; cellular response to hormone stimulus; G protein-coupled receptor signaling pathway; G protein-coupled receptor signaling pathway involved in heart process; intracellular protein transport; regulation of G protein-coupled receptor signaling pathway
Cellular component: adrenomedullin receptor complex; amylin receptor complex 3; cell surface; lysosome; membrane; plasma membrane; receptor complex
Genetic constraint (gnomAD): Loss-of-function variants: 14 observed, 12.48 expected, observed/expected ratio (o/e) 1.12, 90% interval 0.74 to 1.71. The upper end of that interval is the gene's LOEUF score, 1.71, which puts it in group 6 of 6, group 1 being the genes least tolerant of losing a copy. Missense variants: 200 observed, 198.14 expected, observed/expected ratio (o/e) 1.01, 90% interval 0.9 to 1.13. Synonymous variants: 106 observed, 83.96 expected, observed/expected ratio (o/e) 1.26, 90% interval 1.08 to 1.48.
Homologues: Orthologues: chimpanzee RAMP3 (98% identical), macaque RAMP3 (96% identical), mouse Ramp3 (84% identical), rat Ramp3 (79% identical), dog RAMP3 (77% identical), pig RAMP3 (72% identical), guinea pig RAMP3 (70% identical), zebrafish RAMP3 (30% identical). Paralogues in human: RAMP1 (30% identical), RAMP2 (27% identical).
Diseases named in the same sentence as RAMP3 in open-access papers:
RAMP3 is named in the same sentence as 49 diseases in open-access papers, as found by Europe PMC text mining. Sharing a sentence is not in itself a finding about the gene and the disease. The quoted sentences say what the papers report.
breast carcinoma (6 papers, 2017 to 2024). "Previous investigations also revealed that in breast cancer, RAMP3 expression was associated with cancer cell invasion, tumor development, and EMT." (PMID 34611125, 2021). "The inhibition of LOXL2 with shRNA caused a mesenchymal-to-epithelial transition in breast cancer cells and a reduced invasive phenotype; these effects were then reversed using recombinant RAMP3." (PMID 28845385, 2017). "Studies have reported that RAMP3 is highly expressed in a number of cancers, such as glioblastoma, renal carcinoma and breast cancer." (PMID 36081504, 2022). "Recently, a link between LOXL2 and RAMP3 expression has been found in many different cancer cell lines including MDA-MB-231, a metastatic breast cancer cell line." (PMID 28845385, 2017). "The nuclear action of LOXL2 in the invasion and tumorigenesis of breast cancer cells is also mediated, at least in part, through the upregulation of the receptor activity-modifying protein 3 (RAMP3) gene, although the implication of RAMP3 in EMT has not been investigated yet." (PMID 37762708, 2023).
liver cancer (5 papers, 2022 to 2024). An epithelial or non-epithelial malignant neoplasm that arises from the liver. "Several of these genes have been previously linked to cancer, such as RAMP3, which has been shown to inhibit the metastatic ability of liver cancer cells when lacking in cancer fibroblasts." (PMID 37275878, 2023). "RAMP3 levels are thought to increase before the development of liver cirrhosis and it may have protective roles in liver cancer." (PMID 35360852, 2022).
glioblastoma (3 papers, 2014 to 2022). The most malignant astrocytic tumor (WHO grade IV). "Relevant studies have proved that the mRNAs of CALCRL/RAMP2 and CALCRL/RAMP3 are highly expressed in glioblastoma cell lines." (PMID 34712139, 2021). "Real-time quantitative RT-PCR was used to study expression of AM, RAMP2, RAMP3, and CLR in pilocytic astrocytoma and glioblastoma." (PMID 25475159, 2014). "Interestingly, although there were not differences in RAMP2 or RAMP3 expression, AM mRNA expression was induced in glioblastoma whereas it was barely detectable in pilocytic astrocytoma when subjected to hypoxic conditions." (PMID 25475159, 2014).
hepatocellular carcinoma (3 papers, 2022 to 2023). A malignant tumor that arises from hepatocytes. "Third, although we have demonstrated that RAMP3 can inhibit the proliferation, migration and invasion of hepatocellular carcinoma cells, the underlying mechanisms need to be further investigated in vivo." (PMID 37275878, 2023). "We hypothesized that RAMP3 might also be associated with the proliferation, migration and invasive ability of hepatocellular carcinoma cells." (PMID 37275878, 2023). "Furthermore, we found that RAMP3 was associated with idarubicin, which has been shown to improve remission rates in intermediate stage hepatocellular carcinoma, suggesting the possibility that RAMP3, like other small molecule drugs being investigated, could be a new drug target." (PMID 37275878, 2023). "Idarubicin is not only the most toxic drug to human hepatocellular carcinoma cell lines, but also has the ability to overcome multidrug resistance, suggesting to us the possibility of RAMP3 being a drug target." (PMID 37275878, 2023). "We demonstrated at the cellular level that overexpression of RAMP3 significantly reduced the proliferation, migration and invasion of hepatocellular carcinoma cells." (PMID 37275878, 2023). "To date, studies have shown that RAMP3 is overexpressed in hepatocellular carcinoma patients and that RAMP3 is an independent prognostic factor for overall survival and RFS57." (PMID 36202977, 2022). "Furthermore, we demonstrated at the cellular level that RAMP3 correlates with the proliferation, migration, and invasive ability of hepatocellular carcinoma cells." (PMID 37275878, 2023). "The “five-gene” score (TAF9, RAMP3, HN1, KRT19, and RAN) was built to evaluate the genetic role in hepatic carcinoma and reported strong prognostic relevance." (PMID 35200757, 2022). "RAMP3 has been selected by multiple algorithms and ranked highly in random forests; therefore, we believe that RAMP3 is a key gene in lysosomal-related genes and that RAMP3 has not been studied in hepatocellular carcinoma." (PMID 37275878, 2023).
melanoma (3 papers, 2017 to 2023). A malignant, usually aggressive tumor composed of atypical, neoplastic melanocytes. "With the exception of parathyroid adenomas and melanomas, the tumour specimens in all cases exhibited only low expression of RAMP3." (PMID 36835377, 2023). "Melanoma cells were also strongly labelled for AM, CLR, RAMP2, and RAMP3 in melanoma metastatic tissue (patients #1, 2, 3), while mild staining can be observed in melanoma primitive tissue (patient #4)." (PMID 36497391, 2022). "With the exception of melanomas, the tumour specimens exhibited minimal expression of RAMP3." (PMID 36835377, 2023). "Antibodies were used to label serial sections of melanoma tissue with corresponding AM, CLR, RAMP2, and RAMP3 proteins." (PMID 36497391, 2022). "Furthermore, in melanomas, the expression levels of AM, CLR, RAMP2, and RAMP3 have been shown to be higher than those in the control tissues." (PMID 29179449, 2017).
pancreatic cancer (3 papers, 2016 to 2022). "RAMP3-/- CAFs inhibited the proliferation and migration of Pan02 pancreatic cancer cells when co-cultured with Pan02 cells." (PMID 35625516, 2022). "In RAMP3-/- mice, spleen injection of PAN02 murine pancreatic cancer cells showed significantly reduced liver metastasis." (PMID 33614646, 2021). "Moreover, primary cultured RAMP3-/- CAFs inhibited proliferation, migration, and metastasis in co-cultures with PAN02 murine pancreatic cancer cells in vitro and in vivo." (PMID 33614646, 2021). "In the present study, pancreatic cancer cells secreted high levels of adrenomedullin (ADM), and CD11b+ myelomonocytic cells expressed all components of ADM receptors, including GPR182, CRLR, RAMP2 and RAMP3." (PMID 27391260, 2016).
migraine (2 papers, 2023 to 2024). "OPRM1 emerges as a pivotal hub, instigating the activation of GNAS and GNB1, subsequently influencing proteins such as RAMP1, RAMP2, RAMP3, CALCB, CALCR, and SLC5A2 all implicated in migraine attacks." (PMID 39215033, 2024). "Of relevance for migraine pathophysiology, TG satellite glial cells of rat express the canonical CGRP receptor (CLR/RAMP1), along with other CGRP receptors including the AM2 (CLR/RAMP3) and AMY3 (CTR/RAMP3) receptors." (PMID 37628733, 2023).
thymic lymphoma (2 papers, 2022 to 2023). "AMY induces apoptosis in thymic lymphoma via the RAMP3/CT receptor." (PMID 36980580, 2023).
acute respiratory distress syndrome (1 paper, 2025). Progressive and life-threatening pulmonary distress in the absence of an underlying pulmonary condition, usually following major trauma or surgery. "In an LPS-induced acute respiratory distress syndrome (ARDS) mouse model, RAMP2 and RAMP3 were found to play crucial roles inflammatory modulation functions of ADM." (PMID 40565016, 2025).
amyotrophic lateral sclerosis (1 paper, 2021). Amyotrophic lateral sclerosis (ALS) is a neurodegenerative disease characterized by progressive muscular paralysis reflecting degeneration of motor neurons in the primary motor cortex, corticospinal tracts, brainstem and spinal cord. "Differential methylation was reported in RAD9B and C8orf46, CCNF, DPP6, RAMP3, and CCS genes in monozygotic twins and triplets discordant for amyotrophic lateral sclerosis." (PMID 34200232, 2021).
asthma (1 paper, 2022). "In addition, disruption of the adrenal medulla (ADM - a ligand for RAMP3) is associated with airway smooth muscle hyperplasia and contributes to changes in vascular leakage and epithelial repair in asthma." (PMID 36439114, 2022).
calcification (1 paper, 2020). Process by which organic tissue becomes hardened by the physiologic deposit of calcium salts. "CRLR/RAMP3 may mediate the protection of IMD1-53 in aging-associated vascular calcification." (PMID 32229709, 2020).
cardiac hypertrophy (1 paper, 2020). "In a further independent study, on the other hand, the left ventricle of rats with aortocaval shunt-induced cardiac hypertrophy presented up-regulated gene expressions of AM, Calcrl, Ramp2, and Ramp3 compared with controls five weeks after the surgery." (PMID 33489885, 2020). "Regardless of the apparent sexual dimorphism, Ramp3 expression is consistently up-regulated in rodent models of cardiac hypertrophy, hypertension and heart failure, leading to the hypothesis that increased AM signaling through AM2 may have a cardioprotective aim." (PMID 33489885, 2020).
chromophobe renal cell carcinoma (1 paper, 2023). Chromophobe renal cell carcinoma is a rare subtype of renal cell carcinoma, originating from the intercalating cells of the collecting ducts and macroscopically manifesting as a well-circumscribed, highly lobulated, solid tumor that is usually diagnosed at an early stage. "AM, CLR, and RAMP2 were observed in the carcinomatous epithelial compartment of chromophobe renal cell carcinoma (CRCC), and RAMP3 was only found in the inflammatory cells that infiltrated tumors." (PMID 36980580, 2023).
colorectal cancer (1 paper, 2023). A primary or metastatic malignant neoplasm that affects the colon or rectum. "CLR, RAMP2, and RAMP3 expressions have been reported in colorectal cancer; high levels of AM, CLR, RAMP2, and RAMP3 correlate with lymph nodes and distant metastasis, and a high level of AM correlates with a low disease-free survival." (PMID 36980580, 2023).
gastric cancer (1 paper, 2017). A primary or metastatic malignant neoplasm involving the stomach. "Our results show that the expression levels of AM, CRLR, RAMP1, RAMP2, and RAMP3 are higher in gastric cancer tissues than in the adjacent non-tumor gastric tissues, and the patients with the lower expression levels of AM lived longer (p=0.0258)." (PMID 29179449, 2017).
heart failure (1 paper, 2022). Inability of the heart to pump blood at an adequate rate to meet tissue metabolic requirements. "Cardiac myocyte-specific RAMP2 knockout mice showed early onset of heart failure as well as abnormal mitochondrial morphology and function, whereas RAMP3-/- mice exhibited abnormal cardiac lymphatics and a delayed onset of heart failure." (PMID 35625516, 2022).
Hyperglycemia (1 paper, 2022). An increased concentration of glucose in the blood. "Our results showed that glucose dose-dependently increased mRNA expressions of ADM and its receptor components CRLR, RAMP2 and RAMP3 suggesting the association between hyperglycemia and elevated ADM in diabetic patients." (PMID 35390031, 2022).
lung carcinoma (1 paper, 2022). "It has roles in glutamine uptake and supporting the cell malignant capabilities of lung cancer cells’ RAMP3 function as a single transmembrane-spanning protein, which acts as molecular chaperone and allosteric modulator of G-protein-coupled receptors and their signaling pathways." (PMID 36081504, 2022).
lymphedema (1 paper, 2022). Excess fluid collection in tissues, causing swelling. "In contrast, adult RAMP3 knockout (RAMP3-/-) mice showed exacerbated postoperative lymphedema with abnormal lymphatic drainage." (PMID 35625516, 2022). "Although RAMP3-/- mice do not show developmental abnormalities, adults show lymphatic dysfunction and exacerbated postoperative lymphedema." (PMID 35625516, 2022).
Obesity (1 paper, 2024). Accumulation of substantial excess body fat. "Knockout of Ramp3 in ovariectomized mice showed elevated serum insulin levels accompanied by exacerbation in obesity, adipocyte hypertrophy, and adipose tissue weight gain." (PMID 38931172, 2024).
osteosarcoma (1 paper, 2022). A usually aggressive malignant bone-forming mesenchymal neoplasm, predominantly affecting adolescents and young adults.
pneumonia (1 paper, 2014). An acute, acute and chronic, or chronic inflammation focally or diffusely affecting the lung parenchyma, caused by an infection in one or both of the lungs (by bacteria, viruses, fungi, or mycoplasma.). "Pneumonia resulted in an increase of RAMP1 to RAMP3 expression, while MV markedly reduced mRNA levels of RAMP1 to RAMP3 in pneumonia." (PMID 24731244, 2014). "In summary, reduced expression of RAMP1 to RAMP3 under MV in pneumonia was observed, suggesting weakened protection of endothelial integrity due to reduced endogenous AM function." (PMID 24731244, 2014). "Notably, treatment with AM did not alter expression of AM, CRLR or RAMP1 to RAMP3 in pneumonia and subsequent MV." (PMID 24731244, 2014).
sarcoidosis (1 paper, 2025). Sarcoidosis is a multisystemic disorder of unknown cause characterized by the formation of immune granulomas in involved organs. "Among the twelve common DEGs, SALL4, WNT10A, RASAL1, CAMK2B were significantly upregulated while GADD45B, KLF4, OLR1, CSF3, WIF1, RAMP3 and AGER downregulated in both sarcoidosis and LC as compared to the controls." (PMID 40797277, 2025).
uveitis (1 paper, 2025). An inflammatory process affecting a part of or the entire uvea. "Exogenous AM administration tended to increase RAMP2 expression, whereas RAMP3 expression remained suppressed, suggesting that AM administration ameliorates the pathogenesis of uveitis via RAMP2 but not RAMP3." (PMID 40465267, 2025).